TNF (tumor necrosis factor)
Diseases named in the same sentence as TNF in open-access papers (continued):
Sharing a sentence is not in itself a finding about the gene and the disease.
sarcoidosis (continued). "Both are located in regulatory regions of the gene and, strikingly, one of them, –308 A > G, was shown to decrease the response to TNF inhibitors (adalimumab or infliximab) in patients with refractory sarcoidosis." (PMID 32823753, 2020). "Further in vitro studies showed that tumor necrosis factor (TNF)-α (a vitamin D3 antagonist) mediates the suppression of SRC3, leading to alveolar macrophage cathelicidin deficiency in severe sarcoidosis." (PMID 33659946, 2020). "The dosing of TNF blockers used in sarcoidosis at our center is different than the typical dose for rheumatologic conditions with a maintenance dose of every four weeks (5 mg/kg) for infliximab, in line with the current experience-based recommendations." (PMID 32487134, 2020). "Both studies highlighted the variability in TNF-α detection in sarcoidosis patients, as well as the diffuse lung detection compared to higher resolution 18F-FDG." (PMID 32582173, 2020). "Unselected BAL cells from sarcoidosis subjects co-cultured with MSCs showed a reduction in TNF-α (pro-inflammatory M1) and an increase in IL-10 (anti-inflammatory M2) in 9 of 11 samples studied." (PMID 31963936, 2020). "Sarcoidosis is a multisystem granulomatous inflammatory disease propelled primarily by dysregulated macrophage TNF-α production and increased T-helper-1 (Th1 and Th17) cell proliferation." (PMID 31963936, 2020). "Two randomized controlled trials have investigated infliximab, a chimeric monoclonal anti-TNF-α antibody, therapy in sarcoidosis and showed significant though modest improvement in lung function after 14 weeks of treatment." (PMID 33330556, 2020). "Several studies of biological agents that target TNF-α have reported their efficacy and appear today as a second line option in refractory sarcoidosis." (PMID 33330556, 2020). "A large French nationwide multicentric retrospective study on 132 patients with refractory sarcoidosis showed TNF-antagonists to be efficient in about two-thirds of patients, despite higher rates of adverse events." (PMID 33330556, 2020). "Two clinical studies report using 99mTc radiolabeled TNF-α mAb infliximab for scintigraphy imaging to both monitor refractory sarcoidosis disease activity and evaluate potential patient response to anti-TNF-α treatment." (PMID 32582173, 2020). "Recently, BAL cells from sarcoidosis subjects co-cultured with MSCs showed a reduction in TNF-α (pro-inflammatory M1) and an increase in IL-10 (anti -inflammatory M2)." (PMID 32751786, 2020). "HLA-DRB1*0301/ DQB1*0201, transforming growth factor β (TGF-β), tumor necrosis factor α (TNF-α), and Toll-like receptor 4 (TLR-4) are all considered significant indicators for susceptibility to sarcoidosis." (PMID 32290254, 2020). "Bronchoalveolar lavage (BAL) cells from patients with sarcoidosis produce more TNF-α and IL-6 in response to TLR2 agonists compared to healthy controls, while PBMCs from sarcoidosis patients have impaired TLR2 responses." (PMID 32722050, 2020). "Different pro-inflammatory cytokines such as interleukin (IL)-8, IL-12, IL-6, and tumor necrosis factor-alpha (TNF-α) have been shown to be highly expressed in sarcoidosis-affected tissues." (PMID 33330556, 2020). "In this setting, biological agents that target the tumor necrosis factor (TNF) have been introduced as a third-line therapy and have proved to be effective in a proportion of patients with severe/refractory sarcoidosis." (PMID 33330556, 2020). "Tumour Necrosis Factor (TNF) is a participatory cytokine in many inflammatory disorders and plays a role in the formation & propagation of sarcoid granulomas." (PMID 32782876, 2020). "Cytokine production in sarcoidosis was initially featured by an increase in Th1 cytokines (IL-2, IL-6, IL-12, IL-18, TNFα, IFNγ), which is potentially responsible for the so-called classical (M1) macrophage activation." (PMID 32751786, 2020).
sarcoidosis (continued). "Despite their excellent safety profile in other rheumatic conditions, TNF-α antagonists use showed to be less well tolerated with severe infections and malignancies being more frequent during sarcoidosis treatment." (PMID 33330556, 2020). "Paradoxical reactions have been described with anti-TNF therapy in various inflammatory diseases and sarcoidosis-like lesions are increasingly reported during anti-TNF treatment." (PMID 32823753, 2020). "These positive effects of TNF inhibition are supported by a high relapse rate after discontinuation of infliximab therapy in 47 patients with severe sarcoidosis." (PMID 33330556, 2020). "ELISA measurements of these co-culture supernatants showed that BAL cells from sarcoidosis subjects significantly decreased their TNF-α production (p = 0.029) and increased their IL-10 production (p = 0.011), unlike cells from control subjects." (PMID 31963936, 2020). "Alveolar macrophages isolated from sarcoidosis patients are in an activated state and produce significantly higher levels of inflammatory cytokines, such as TNF-α compared with control AMs." (PMID 31963936, 2020). "In human sarcoidosis, TNF-α production in alveolar macrophages is higher in sarcoidosis patients than in healthy controls and reflects disease activity." (PMID 31515495, 2019). "Next, we measured serum levels of cytokines such as IFN-γ, TNF-α, and IL-17 to examine the association of MAIT cells with cytokines in sarcoidosis patients." (PMID 31515495, 2019). "On the other hand, systemic inflammation and TNF-alpha response have also been implicated in COPD and sarcoidosis." (PMID 31842375, 2019). "While infliximab is considered a therapeutic option for sarcoidosis refractory to steroids, paradoxical reactions can occur with TNF-alpha inhibitors." (PMID 30064495, 2018). "To detect variants predisposing to sarcoidosis and to identify genetic differences between patient subgroups, we studied four genes in the MHC Class III region (LTA, TNF, AGER, BTNL2) and HLA-DRA with tag-SNPs and their relation to HLA-DRB1 alleles." (PMID 28469621, 2017). "HLA-DR allele and cytokines such as tumor necrosis factors (TNF-α, TNF-β) are overexpressed in sarcoidosis as well and correlated with fibrosis development." (PMID 28652588, 2017). "The importance of TNF in sarcoidosis has been validated by studies documenting effectiveness of biologic TNF antagonists in sarcoidosis in treating some patients with sarcoidosis." (PMID 29163767, 2017). "After co-stimulation of PBMCs with FCWAs and LPS, the production of TNF-α, IL-6, IL-10 and IL-12 was significantly higher in patients with sarcoidosis, compared to healthy subjects (1.7-fold, 2.0-fold, 2.2-fold, and 2.8-fold, respectively; all p < 0.05)." (PMID 27688795, 2016). "Monocytes appeared to be responsible for elevated TNF and IL-6 responses in sarcoidosis patients, so monocyte subsets were characterised based on relative expression of CD14 and CD1624." (PMID 27929051, 2016). "Monocytes are shown to be a source of TNF and IL-6 within stimulated whole blood assays, and monocytes from sarcoidosis patients produced these cytokines to a greater extent than healthy volunteers." (PMID 27929051, 2016). "Based on the simultaneous development of sarcoidosis and cutaneous vasculitis, the patient was diagnosed as having a series of paradoxical inflammations during anti-TNF-α therapy." (PMID 26864464, 2016). "The importance of TNF alpha in granuloma formation led to proposing this cytokine as a therapeutic target in sarcoidosis." (PMID 27795804, 2016). "In 2010, Ramos-Casals and colleagues reported that there had been 38 cases of sarcoidosis or “sarcoid like” granulomatous disease during anti-TNF-α therapy out of 1370 adult patients of systemic autoimmune diseases under the use of biological agents." (PMID 26864464, 2016).
sarcoidosis (continued). "Our results showed that patients with sarcoidosis, compared to healthy subjects, had a significantly higher secretion of inflammatory cytokines TNF-α, IL-6, IL-10 and IL-12, after co-stimulation of PBMCs with FCWAs and LPS." (PMID 27688795, 2016). "We demonstrated previously that after in vitro stimulation of PBMCs with FCWAs alone, the secretion of TNF-α, IL-6, IL-10 and IL-12 was higher in patients with sarcoidosis compared to healthy subjects." (PMID 27688795, 2016). "The main results obtained from this study show that patients with sarcoidosis had a significantly higher secretion of inflammatory cytokines TNF-α, IL-6, IL-10 and IL-12 after in vitro co-stimulation of PBMCs with FCWAs and LPS." (PMID 27688795, 2016). "In sarcoidosis monocytes, stimulated intracellular TNF accumulation was significantly greater than in healthy controls." (PMID 27929051, 2016). "In cases of steroid resistant sarcoidosis and when at least one other immunosuppressive agent has been tried, TNF-alpha inhibitors have shown promise." (PMID 26904327, 2016). "Significantly higher concentrations of secreted TNF and IL-6 were found in stimulated whole blood from patients with sarcoidosis compared with healthy controls." (PMID 27929051, 2016). "Stimulated whole blood and monocytes from patients with sarcoidosis produced more TNF and IL-6 compared with healthy controls." (PMID 27929051, 2016). "This was attributed to production of the cytokines IL-6 and TNF at the site of inflammation; similar findings have also been reported for sarcoidosis." (PMID 25770018, 2015). "Vitreous levels of IL-4, IL-17A, IL-22, IL-31, and TNFα in PDR patients were also significantly higher than those of sarcoidosis patients." (PMID 26352837, 2015). "In patients with active sarcoidosis, the release of TNFα by activated alveolar macrophages has been widely documented in a lot of previous studies." (PMID 25866780, 2015). "During routine examinations of the patient who had been followed for psoriasis vulgaris for 20 years and who had been on several anti-TNF regimens thereafter, new pulmonary pathologies due to sarcoidosis were detected." (PMID 26425632, 2015). "Considering the radiological and pathological findings, the patient was diagnosed with stage 2 sarcoidosis and was suggested to discontinue anti-TNF treatment." (PMID 26425632, 2015). "An autoimmune mechanism involving T cells—specifically TH1 cells—and tumor necrosis factor alpha plays a fundamental role in the development of sarcoidosis." (PMID 26083934, 2015). "In the present study, we have used 99mTechnetium (99mTc) labelled infliximab in patients with newly diagnosed sarcoidosis for noninvasive in vivo scintigraphic evaluation of the presence of TNFα in pulmonary and lymph nodal sarcoid lesions." (PMID 25866780, 2015). "Unstimulated BAL cells of patients with sarcoidosis already produced more TNF-α compared to control BAL cells, as shown by many groups." (PMID 26204953, 2015). "Although debates regarding the treatment still continue, there is some information about sarcoidosis development, thanks to anti–tumor necrosis factor (TNF) agents used in steroid-resistant sarcoidosis and relapses during systematic involvement." (PMID 26425632, 2015). "Previous studies from our group showed decreased expression of Th1 cytokines (INFγ and TNFα in BAL fluid cells in HLA-DR3+ sarcoidosis patients (typically with Löfgren’s syndrome) as compared with HLA-DR3− patients." (PMID 25969669, 2015). "TNF-α is a pro-inflammatory cytokine previously shown to play a critical role in the pathogenesis of Th1 responses and to be elevated in sarcoidosis patients." (PMID 25866481, 2015). "Recently, the use of anti-tumor necrosis factor alpha (anti-TNFα) agents has been introduced for therapy of chronic and refractory sarcoidosis." (PMID 25866780, 2015).
sarcoidosis (continued). "There were also differences in serum inflammatory markers between these two groups of sarcoidosis patients with patients with pulmonary sarcoidosis having greater levels of TNF-α and IL-8 than EPS and control subjects." (PMID 25866481, 2015). "The examples of specific anti-TNF agents being used in refractory sarcoidosis, refractory Behcet's disease, and refractory uveitis are referenced and discussed at length." (PMID 26221543, 2015). "Other brain conditions in development for treatment with the same specific anti-TNF agents include the cognitive defects seen after surgery, after irradiation, after chemotherapy, and in sarcoidosis and RA." (PMID 26221543, 2015). "This is especially the case in “orphan diseases” such as rare IMIDs, in which it is very difficult to conduct RCTs, but it also holds true for more common diseases as exemplified by infliximab (anti-TNF) treatment for refractory sarcoidosis." (PMID 26697019, 2015). "In refractory patients, TNF-α inhibitors are invaluable, with many successful cases of sarcoidosis treatment with infliximab and adalimumab reported in the literature." (PMID 25494723, 2014). "The ability of tacrolimus to inhibit both hapten-induced production of Th1 cytokines and the production of TNF-alpha by T cells and macrophages constitutes an effective rational for its use in the treatment of sarcoidosis." (PMID 24826355, 2014). "According to literature, infliximab and adalimumab, which bind both soluble and membrane bound TNF-α, seem to be more effective in sarcoidosis than etanercept, which binds only to soluble TNF-α with incomplete inhibition of TNF-α bioactivity." (PMID 25494723, 2014). "Prospective, randomized,controlled trials assessing anti-TNF-α agents are needed in order to evaluate theirefficacy in cases of sarcoidosis with rheumatic complications." (PMID 24831403, 2014). "Although different to the expected action of TNF-α in vasculitis, with the extended use of anti-TNF-α agents in diverse clinical scenarios, rare adverse events, including granulomatous diseases such as sarcoidosis and GPA, have been described." (PMID 24707429, 2014). "Some treatments are known to trigger sarcoidosis such as interferon-α35 or anti-tumor necrosis factor α,36 but patients receiving those treatments were excluded from our study." (PMID 25380084, 2014). "Eight months later, another period of treatment efficacy loss followed, associated with NAbs against adalimumab, reducing the choice of TNF-α inhibitors described as beneficial in sarcoidosis." (PMID 25494723, 2014). "In sarcoidosis, TNF-α induced the expression of intracellular adhesion molecule-1 (ICAM-1) on AMs, leading to cellular aggregation." (PMID 24339826, 2013). "In this study, we aimed to investigate the association of six well-characterized polymorphisms in tumor necrosis factor alpha and beta (TNF-α and TNF-β) genes with the risk for sarcoidosis via a comprehensive meta-analysis." (PMID 24244632, 2013). "On the one hand, the role of TNF-α in sarcoidosis seems to be partial and to change as the disease evolves." (PMID 23983404, 2013). "To generate more information, we carried out a meta-analysis of all available case-control studies to investigate the association of genetic polymorphisms of TNF-α and TNF-β with the risk of sarcoidosis." (PMID 24244632, 2013). "By contrast some studies reported refractory sarcoidosis cases successfully treated by TNFα blockers especially adalimumab and infliximab." (PMID 24373564, 2013). "Infliximab (chimeric monoclonal antibody against TNF-α), etanercept (soluble TNF receptor that binds to TNF in circulation), and adalimumab (humanized monoclonal antibody against TNF) are agents that are rarely used in the treatment of sarcoidosis." (PMID 23533794, 2013). "A recent study found TNF to be secreted at higher levels in a subset of patients with refractory sarcoidosis." (PMID 23533794, 2013).
sarcoidosis (continued). "Twelve children (7 females, 5 males), of whom 7 were affected by JIA, 3 by idiopathic uveitis, 1 by early-onset sarcoidosis, and 1 by Behçet’s disease, were enrolled in Group 2, who received Adalimumab as second anti-TNF-α drug." (PMID 23587261, 2013). "Given the highly polymorphic sequences of both genes, it is of interest to determine which genetic defects have the causal potentials to regulate plasma TNF-α and TNF-β levels, further to precipitate the occurrence of sarcoidosis." (PMID 24244632, 2013). "In this study, we sought to investigate the association of the TNF-α and TNF-β genetic polymorphisms with sarcoidosis risk from English journals by conducting a meta-analysis of 13 articles and 4100 subjects." (PMID 24244632, 2013). "We are unaware of any studies concerning thyroid function in sarcoidosis patients treated with infliximab or any other TNF-α antagonists." (PMID 24348571, 2013). "A number of studies have been carried out assessing the role of anti TNF-α in treatment of sarcoidosis, but their role remains questionable." (PMID 23320239, 2012). "A possible mechanism for this association is that anti-TNF-α therapies modulate a CD4+ Th1 cytokine response, key to the immunopathogenesis of sarcoidosis." (PMID 23320239, 2012). "Taken together these results indicate that pulmonary sarcoidosis is associated with increased numbers of mature, functionally competent DCs that intrinsically induce increased levels of a central mediator in sarcoidosis, TNFα." (PMID 22513006, 2012). "In spite of this, a number of case reports to date are available highlighting the unexpected development of sarcoidosis following treatment with anti TNF-α, thus their role is controversial in granulomatous conditions." (PMID 23320239, 2012). "When cytokine production was measured by Luminex bead assays, we observed increased TNFα expression in co-cultures of mo-DCs from sarcoidosis patients, when compared with co-cultures of mo-DC from healthy controls." (PMID 22513006, 2012). "Again, although the evidence is limited, leflunomide has been reported as an efficacious alternative therapy in treatment of sarcoidosis, thus offering the possibility of use for patients where sarcoidosis has developed following anti TNF-α therapy." (PMID 23320239, 2012). "On the other hand, anti-TNF-alpha therapies can induce sarcoidosis, including primary cutaneous sarcoidosis." (PMID 21603192, 2011). "Our data indicate that significant associations between serum levels of TNF-α and type I IFN and clinical manifestations exist in a sarcoidosis cohort that differ significantly by self-reported ancestry." (PMID 22195005, 2011). "In our own, unpublished clinical experience, neurosarcoidosis is particularly responsive to anti-TNF-α therapy when compared with other sarcoidosis phenotypes." (PMID 22195005, 2011). "No cytokine differences were observed according to gender, but significant differences in TNF-α level were found between sarcoidosis patients of different ancestral backgrounds." (PMID 22195005, 2011). "Suppression of Treg function, as was demonstrated in the lungs of sarcoidosis patients presumably in response to TNFα, is sufficient to reduce the threshold for a sustained antigen-dependent Th1 response." (PMID 21637752, 2011). "Taking advantage of this better understanding of disease pathogenesis, anti-TNFα agents are being increasingly used to treat refractory sarcoidosis." (PMID 21085534, 2010). "Since granulomatous diseases (e.g., IBD, sarcoidosis) tend to respond better to anti-TNF mAb therapy, etanercept is rarely used to treat IBD." (PMID 20712883, 2010). "Although, we have not measured TNF-α in our patient's EBC, such data would be interesting in the context of the possible application of anti-TNF agents in the treatment of refractory sarcoidosis." (PMID 20420721, 2010).